BRD4 (bromodomain containing 4)
Diseases named in the same sentence as BRD4 in open-access papers (continued):
Sharing a sentence is not in itself a finding about the gene and the disease.
sarcoma (10 papers, 2017 to 2025). A usually aggressive malignant neoplasm of the soft tissue or bone. "Finally, also both gene partners of BRD4-LEUTX have been previously linked to sarcoma." (PMID 36232302, 2022). "FET sarcoma cells are sensitive to BRD4 inhibition, possibly by disrupting the genomic binding of BRD4, FET-FOPs, and SWI/SNF complexes." (PMID 40988026, 2025). "The elevated expression of LEUTX seen in these tumors is in line with a prior study that reported a BRD4::LEUTX fusion in a pediatric sarcoma." (PMID 38500181, 2024). "In three cases (#1, #3, and #4) the fusion transcript involving exon 11 of BRD4 was identical to the one reported in an embryonal CNS tumor and a pediatric sarcoma with epithelioid features." (PMID 38500181, 2024). "Using the dual‐bromodomain inhibitor AZD5153, we show that FET sarcoma cells are sensitive to BRD4 inhibition." (PMID 35182012, 2022). "We used chromatin immunoprecipitation sequencing (ChIP‐seq) to define their genome binding patterns, immunofluorescence analysis to analyze co‐localization and then evaluated the impact of BRD4 inhibition or degradation on FET sarcoma cells." (PMID 35182012, 2022). "Inhibition of BRD4 binding to acetylated chromatin regions such as super‐enhancers is therefore the most plausible mechanism behind the effect of BRD4 bromodomain inhibition on FET sarcoma cells." (PMID 35182012, 2022). "As BRD4 interacts with Cyclin-dependent Kinase 9 (CDK9) in other fusion-driven sarcomas, combinatorial treatment with BRD4 and CDK9 inhibitors may exert synergistic anti-tumor effects in PF+ RMS." (PMID 37345159, 2023). "The aim of this study was to characterize the interactions between FET oncoproteins (FUS‐DDIT3 and EWSR1‐FLI1) and the different SWI/SNF complexes as well as the transcriptional coactivator BRD4, to investigate their roles in FET sarcoma." (PMID 35182012, 2022). "When evaluated on protein level in sarcoma cell lines, the three tested antibodies demonstrated substantial variations in the detection of BRD4 isoforms while there was no apparent difference between cell lines." (PMID 35182012, 2022). "BRD4 remained bound up to 1000 mm KCl, indicating a strong interaction in FET sarcoma cells." (PMID 35182012, 2022). "Therefore, we first evaluated the expression of BRD4 and its two main isoforms; the short (80 kDa) and the long isoform (150 kDa) in FET sarcoma tissues and cells." (PMID 35182012, 2022). "In vitro cell viability studies showed that cell lines from FET sarcomas (MLS 2645‐94, 402‐91 and 1765‐92, and EWS TC‐71) were more sensitive to BRD4 inhibition with the dual‐bromodomain inhibitor AZD5153 compared to HT1080 fibrosarcoma cells or normal fibroblasts." (PMID 35182012, 2022).
small cell lung carcinoma (10 papers, 2017 to 2025). Small cell lung cancer (SCLC) is a highly aggressive malignant neoplasm, accounting for 10-15% of lung cancer cases, characterized byrapid growth, and early metastasis. "ACY-1215 combined with the BRD4 inhibitor (JQ1) inhibited the growth of xenograft tumors from small cell lung cancer cells by stimulating NK cell-mediated immune activity." (PMID 38231305, 2024). "Intriguingly, ASXL3, similar to ASXL1 and ASXL2, forms a PR-DUB complex with BAP1 but also exclusively interacts with BRD4, which binds to acetylated histones via its bromodomains in small cell lung carcinoma." (PMID 38791157, 2024). "Unbiased high-throughput drug combination screens reveal that PI3K-AKT-mTOR pathway inhibitors exert synergistic anticancer effects with BRD4 inhibitors against small cell lung cancer cells, and mTOR inhibitors exhibit the best synergy." (PMID 38135679, 2023). "In multiple patient-derived xenograft models of small cell lung cancer, combination therapy with the mTOR inhibitor Everolimus and the BRD4 inhibitor NHWD870 synergistically induce cancer cell apoptosis and blocks tumor progression without significantly increasing toxicity to normal tissues in mice." (PMID 38135679, 2023). "Notably, we could confirm the dominant-negative phenotype of Brd4 mutants in the non-small cell lung carcinoma cell line H1299." (PMID 28490802, 2017). "A study demonstrated that ASXL3 forms an oncogenic axis with BRD4 and BAP1, activating ASCL1/MYCL/E2F signaling in small cell lung cancer." (PMID 38791157, 2024). "Genome-wide CRISPR-Cas9 dropout screen in small cell lung cancer (SCLC) cells identified PAX9 as an essential factor that is overexpressed and is transcriptionally driven by the BAP1/ASXL3/BRD4 epigenetic axis." (PMID 35628401, 2022). "In small cell lung cancer patients, BRD4 interacts with ASXL3 but not ASXL1 or ASXL2." (PMID 38791157, 2024).
acute lymphoblastic leukemia (9 papers, 2016 to 2026). Leukemia with an acute onset, characterized by the presence of lymphoblasts in the bone marrow and the peripheral blood. "Similarly, butyrylation or crotonylation of H4K5 (as opposed to its acetylation) via the aberrant activation of FAST kinase domains 1 in acute lymphoblastic leukemia models reduce BRD4’s association with the chromatin." (PMID 35402505, 2022). "To test GeneWalk on another well-characterized model system, we reanalyzed published NET-seq data describing the response of a human T-cell acute lymphoblastic leukemia (T-ALL) cell line to treatment with JQ1, a small molecule that targets the BET bromodomain in BRD4 and other BET family members." (PMID 33526072, 2021).
diabetes (9 papers, 2020 to 2026). "Two hundred twenty‐two young patients with diabetes are also recruited for whole exome sequencing (WES) to screen for BRD4 mutations." (PMID 40539402, 2025). "BRD4 is linked to a variety of aging-related diseases, such as ischemic brain injury, cardiovascular disease, pulmonary fibrosis, diabetes, and cancer." (PMID 35308165, 2022). "Adjusted for age, weight, waist circumference, drinking, smoking, hypertension, and diabetes, high pulse pressure risk was significantly higher for carriers with the rs4808278-TT genotype in BRD4 than those with wild genotypes (OR: 0.400, 95% CI: 0.217–0.737, P* < 0.05)." (PMID 33148187, 2020). "Therefore, we speculate that Pin1 and BRD4 are important regulatory proteins of diabetes that promote macrovascular disease, but the underlying mechanism is still unclear." (PMID 32774672, 2020). "In this study, 222 young diabetes patients were recruited, and whole exome sequencing (WES) was performed to screen for BRD4 mutations." (PMID 40539402, 2025). "By elucidating the regulatory networks governed by BRD4 in pancreatic β cells, our study revealed that the therapeutic targeting of the BRD4 pathway represents a potent and promising strategy for treating diabetes." (PMID 40539402, 2025). "This study elucidated the role played by the Pin1/BRD4 pathway in diabetes- induced GC progression, and provides a theoretical basis for finding and screening new targets for antidiabetic tumor drugs." (PMID 35461311, 2022). "It is found that p.R749C can significantly affect BRD4 signaling and might play roles in diabetes development in patients." (PMID 40539402, 2025). "In addition, it was found that BRD4 inhibited the expression of MMP-13 in diabetics-related degeneration of intervertebral disc via modulating autophagy, NF-κB, and MAPK pathways." (PMID 33849578, 2021). "Antagonizing the Pin1/BRD4 pathway may be a feasible method for preventing and treating macrovascular disease in patients with diabetes." (PMID 32774672, 2020). "Taken together, these data indicate that BRD4‐mediated regulatory networks play crucial roles in regulating β cell differentiation and that targeting BRD4 signaling with more carefully designed chemicals may hold promise for developing novel therapeutic strategies for diabetes." (PMID 40539402, 2025). "Apabetalone is already in clinical trials for treatment of different diseases like atherosclerosis, diabetes, Alzheimer’s disease, and chronic kidney disease, and it covalently binds to the BD2-domain of BRD4." (PMID 36364277, 2022). "Per statistical analysis of the ΔΔCT scores, BRD4 expression is significantly increased in the retinas of STZ-diabetic mice; 8 months after diabetes was confirmed." (PMID 34456740, 2021). "However, whether BRD4 mutations are relevant to diabetes development is not known." (PMID 40539402, 2025).
pancreatic ductal adenocarcinoma (9 papers, 2017 to 2023). An infiltrating adenocarcinoma that arises from the epithelial cells of the pancreas. "Moreover, BRD4 inhibits autophagy in human pancreatic ductal adenocarcinoma cells by associating with G9a." (PMID 36158208, 2022). "To validate the screening results, we knocked down the genes encoding BRD2, BRD3, or BRD4 in human pancreatic ductal adenocarcinoma KP-4 cells and determined their effects on autophagy by monitoring the levels of the lipidated form of LC3 (LC3II)—a marker of autophagosome formation/accumulation." (PMID 28525743, 2017). "Increasing data show dual inhibition of HDACs and BRD4 as a promising strategy against many tumors, such as pancreatic ductal adenocarcinoma and gallbladder cancer, however, the impacts of dual HDACs/BRD4 inhibition on virus-associated lymphomas including PEL remain unclear." (PMID 36638143, 2023).
rhabdomyosarcoma (9 papers, 2017 to 2024). A rare aggressive malignant mesenchymal neoplasm arising from skeletal muscle. "Similar to PAX3-FOXO1 in rhabdomyosarcoma and EWSR1-associated fusions in Ewing sarcoma, our data indicate a substantial co-localization of BRD4 and FUS-DDIT3, and a BET protein-dependent function of FUS-DDIT3 via physical interaction in MLPS." (PMID 30903020, 2019). "Our work unveils isoform-specific functions of BRD4 in rhabdomyosarcoma." (PMID 38191874, 2024). "PAX3-FOXO1, the fusion gene that is a risk factor for poor prognosis, acts as a super-enhancer dependent on the BET bromodomain protein, BRD4 (bromodomain-containing protein 4), which suggests BRD4 as a treatment target for alveolar rhabdomyosarcoma patients with the PAX3-FOXO1 translocation." (PMID 30487384, 2018). "Inhibition of BRD4 with the BRD4 inhibitor JQ1 or OTX015 abolishes PAX3-FOXO1 function, suppresses alveolar rhabdomyosarcoma cell proliferation in vitro and induces tumor growth inhibition in mouse models." (PMID 38135679, 2023). "In rhabdomyosarcoma (RMS) cell lines, we recently demonstrated that OTX015 specifically downregulates BRD4 and MYC levels, which in turn lead to a marked downmodulation of GNL3 gene." (PMID 33806232, 2021). "In alveolar rhabdomyosarcoma, the chimeric transcription factor PAX3-FOXO1 interacts with the master transcription factors MYCN, MYOG and BRD4 at target gene super-enhancers, resulting in over-expression of SOX8, MYOD1, MYOG and MYCN, alveolar rhabdomyosarcoma tumorigenesis and dependence on BRD4." (PMID 38135679, 2023). "Furthermore, in another fusion‐driven tumour form, rhabdomyosarcoma, the PAX3‐FOXO1 fusion oncoprotein was shown to interact with BRD4 and induce oncogenic transcription in a similar way as EWSR1‐FLI1." (PMID 35182012, 2022).
T-cell acute lymphoblastic leukemia (9 papers, 2020 to 2026). Acute lymphoblastic leukemia of T-cell origin. "Similar to this, BRD4 knockdown in T cell acute lymphoblastic leukemia (TALL) cells change splicing patterns." (PMID 37509171, 2023). "Recent works have demonstrated that BRD4 interacts with components of the spliceosome, and that these interactions can mediate alternative splicing in the context of T cell acute lymphoblastic leukemia." (PMID 37435059, 2023).
chronic obstructive pulmonary disease (8 papers, 2020 to 2025). A chronic and progressive lung disorder characterized by the loss of elasticity of the bronchial tree and the air sacs, destruction of the air sacs wall, thickening of the bronchial wall, and mucous accumulation in the bronchial tree. "In chronic obstructive pulmonary disease, circOSBPL2 sponges miR-193a-5p, leading to increased expression of its downstream target BRD4 and worsening inflammatory responses." (PMID 40862743, 2025). "Our previous studies have suggested that bromodomain protein 4 (BRD4) is increased in the lung of stable chronic obstructive pulmonary disease (COPD) patients, which has been shown to be involved in inflammatory responses." (PMID 36721187, 2023). "miR-29b targets the 3′-UTR of BRD4 to regulate the expression of BRD4 and has an inverse correlation (low miR-29b and high BRD4) in chronic obstructive pulmonary disease (COPD) patients." (PMID 34540900, 2021). "Notably, BRD4 expression levels are elevated in the blood and sputum of patients with chronic obstructive pulmonary disease (COPD)." (PMID 39215370, 2024). "BRD4 is a conserved member of the bromodomain and extra-terminal (BET) family of chromatin readers, which is closely related to inflammation activation in multiple diseases, such as rheumatoid arthritis, pulmonary arterial hypertension, and chronic obstructive pulmonary disease." (PMID 32392533, 2020).
head and neck squamous cell carcinoma (8 papers, 2019 to 2025). A squamous cell carcinoma that arises from any of the following anatomic sites: lip and oral cavity, nasal cavity, paranasal sinuses, pharynx, larynx, and salivary glands. "The miR-204-BRD4 axis has also been noted in head and neck squamous cell carcinoma, in which miR-204 acts as a tumor suppressor by enhancing p27 mRNA stability through targeting BRD4." (PMID 37686037, 2023). "In head and neck squamous cell carcinoma (HNSCC), BRD4 interacts with the YAP1/TAZ/TEAD transcriptional complex to facilitate expression of oncogenes." (PMID 37994501, 2023). "BRD4 was reported to recruit MED1 and p65 to form super-enhancers, and a BRD4 inhibitor was reported to disrupt super-enhancers and decrease the tumorigenic potential of cancer stem cells in head and neck squamous cell carcinoma." (PMID 35842703, 2022). "Additionally, BET inhibition, particularly targeting Bromodomain containing 4 (BRD4), enhances MHC‐I expression and CD8+ T cell‐mediated antitumour immunity in head and neck squamous cell carcinoma (HNSCC)." (PMID 40673641, 2025).
renal fibrosis (8 papers, 2016 to 2025). A final common manifestation of a wide variety of chronic kidney diseases characterized by glomerulosclerosis and tubulointerstitial fibrosis. "In recent research, PRMT1 was reported to mediate BRD4 arginine methylation and phosphorylation thus promoting partial epithelial-mesenchymal transformation and renal fibrosis." (PMID 40612681, 2025). "The BRD4 inhibitor JQ1 can exert anti-renal fibrosis effects through three pathways: attenuation of renal injury, inflammation and oxidative stress." (PMID 39215370, 2024). "Given the importance of BRD4 in the development of renal fibrosis, researchers have investigated the therapeutic effects of other BRD4 inhibitors for renal disease." (PMID 39215370, 2024). "And BRD4 was revealed to regulate renal fibrosis by the modulation of NF-κB phosphorylation and acetylation." (PMID 30455393, 2019). "It was previously revealed that BRD4 regulated renal fibrosis by the modulation of NF-κB phosphorylation and acetylation." (PMID 30455393, 2019). "BRD4 and other BET proteins have been implicated in the upregulation of inflammatory genes in CKD, and BET inhibitors have been studies in preclinical setting for treatment of kidney injury and prevention of renal fibrosis." (PMID 40510153, 2025). "In summary, BRD4 plays an important role in promoting renal fibrosis." (PMID 39215370, 2024). "Inhibition of BRD4 attenuated renal fibrosis by blocking TGF-β-mediated Nox4 expression." (PMID 37737256, 2023). "Two recent articles suggest that BRD4 inhibition could be used as a strategy to treat renal fibrosis." (PMID 28721198, 2017). "To demonstrate whether I-BET151 elicited renal fibrosis reduction was associated with the inhibition of Brd4, we performed immunoblot analysis to examine the effect of I-BET151 on Brd4 expression in the murine kidney collected at 7 days after UUO." (PMID 27732564, 2016). "BRD4 may be an effective target for treating renal fibrosis." (PMID 39215370, 2024). "Brd4 might therefore be one of the BET proteins that regulate development of renal fibrosis." (PMID 27732564, 2016). "Coincident with Brd2 and Brd4 repression, I-BET151 improved renal function and attenuated renal fibrosis." (PMID 33664670, 2021). "Brd4 siRNA largely reduced expression of Brd4.Thus, these results suggest that Brd4 may be a critical component in the mechanism of BET family protein-mediated renal fibrosis." (PMID 27732564, 2016).
Alzheimer disease (7 papers, 2017 to 2025). A progressive, neurodegenerative disease characterized by loss of function and death of nerve cells in several areas of the brain leading to loss of cognitive function such as memory and language. "One of these BET inhibitors, JQ1, is associated with high specificity for Brd4 inhibition and has been shown to exert protective effect in several diseases, including arthritis, heart remodeling, Alzheimer’s disease and stroke." (PMID 32982695, 2020). "Mutations in Brd4 may contribute to the development of Alzheimer's Disease by impairing cell competition." (PMID 39010274, 2024). "Recently, emerging evidence from preclinical studies suggested the potential in developing therapeutics of Alzheimer’s disease (AD) by targeting bromodomain containing protein 4 (BRD4), an epigenetic regulatory protein." (PMID 35248531, 2022). "JQ1 has been previously shown to improve arthritis, heart remodeling, Alzheimer’s disease and stroke by inhibiting Brd4." (PMID 32982695, 2020). "In contrast, a previous study demonstrated that inhibition of Brd4 is able to enhance brain plasticity and improve cognitive performance in an animal model of Alzheimer’s disease." (PMID 32982695, 2020). "This selective upregulation identifies Brd4 as a key mediator of microglial responses to amyloid pathology, underscoring its potential as a promising therapeutic target for neuroinflammation and Alzheimer’s disease (AD)." (PMID 40305227, 2025). "Here we tested the effect of JQ1—a small-molecule inhibitor of the chromatin readers BRD2, BRD3, BRD4 and BRDT—on brain function and show that JQ1 is able to enhance cognitive performance and long-term potentiation in wild-type animals and in a mouse model for Alzheimer’s disease." (PMID 28949335, 2017).
diabetic cardiomyopathy (7 papers, 2021 to 2025). Diabetic cardiomyopathy is a disorder of the heart muscle in people with diabetes. "Moreover, another paper has highlighted that up-regulating BRD4 in diabetic cardiomyopathy causes mitochondrial damage and impairs cardiac function, while down-regulating BRD4 has the opposite effect." (PMID 37878982, 2023). "BRD4 inhibition prevented diabetic cardiomyopathy induced by high-fat diet through activating mediated mitochondrial autophagy." (PMID 37821869, 2023). "BRD4 is a transcriptional and epigenetic regulator which is mechanistically linked to PINK1-Parkin mediated mitophagy in diabetic cardiomyopathy." (PMID 34440882, 2021). "Recently, the role of Bromodomain containing protein 4 (BRD4) on diabetic cardiomyopathy was evaluated." (PMID 34440882, 2021). "Treatment with JQ1, a BRD4 inhibitor, restores PINK1/Parkin-mediated mitophagy and attenuates HFD-induced diabetic cardiomyopathy, highlighting the regulatory role of BRD4 in this pathway." (PMID 40004130, 2025). "Higher BRD4 and lower PINK1 protein expression was observed in a mouse model of high-fat diet-induced diabetic cardiomyopathy." (PMID 34440882, 2021).